USP30 (ubiquitin specific peptidase 30)
Diseases named in the same sentence as USP30 in open-access papers (continued):
Sharing a sentence is not in itself a finding about the gene and the disease.
breast carcinoma (continued). "In vitro experiments verified that knockdown of USP30 inhibited proliferation and EMT in breast cancer, and its overexpression yielded the opposite result." (PMID 38146008, 2024). "Gene expression correlation analysis revealed that USP30 negatively correlates with the expression of stem cell markers such as MMP2, MMP9, MYC, OCT4(POU5F1), NANOG, ALDH1A3, CD133 (PROM1), EPCAM, CD24, and ITGA6 in breast cancer cohorts." (PMID 41306556, 2025). "Clinically, ER‐ and PR‐positive breast cancer tissues showed higher USP30 levels than receptor‐negative cases." (PMID 41306556, 2025). "The results showed that USP30-negative breast cancer patients had a longer disease-free survival time than USP30-positive patients (overall survival)." (PMID 38146008, 2024). "However, we found underexpression of EEF2 and GLRX2 proteins involved in ROS; MTX2 in MMO; USP30 in MIT; TSPO in MIT and PPM processes; BAX in FUS; and MTFR1L and MIEF1 in FIS compared to luminal A and basal-like breast cancer tumors." (PMID 35327574, 2022). "In reviewing the literature, no data were found on the association of breast cancer with PCGF1, RNF123, GRWD1, USP30, ATXN3L, and PARP11." (PMID 36685836, 2022). "Additionally, we performed reverse IP verification, USP30 was detected in Snail immunoprecipitates but was absent in the FLAG control samples, which demonstrated that USP30 and Snail are bound in breast cancer cells." (PMID 38146008, 2024). "In addition, we revealed the role of USP30 in breast cancer progression, EMT progression and deubiquitination of EMT marker proteins by studying and analysing cellular models, mouse models and human breast cancer samples." (PMID 38146008, 2024).
neuroblastoma (5 papers, 2020 to 2025). Neuroblastoma (NB) is the most common solid, extracranial childhood tumor. "Activity-based protein profiling mass spectrometry confirmed target engagement, high selectivity, and potency of USP30inh for USP30 against 49 other deubiquitylating enzymes in a neuroblastoma cell line." (PMID 37385347, 2023). "To be able to compare compound activity to USP30 loss, we used CRISPR/Cas9 to generate YFP-Parkin-RPE1 (retinal pigment epithelium) and SHSY5Y (neuroblastoma) USP30 KO cells." (PMID 32636217, 2020). "The inhibitor demonstrated high potencyand selectivity for endogenous USP30 in neuroblastoma cells." (PMID 39804742, 2025). "Using a biophysical and structuralproteomics approach similar to our previous work, we show that USP30-I-1 is highly selectiveand potent against endogenous USP30 when compared to the >40 otherendogenous DUBs identified in the neuroblastoma-derived SH-SY5Y cellline." (PMID 39804742, 2025). "Knockout of the Usp30 gene upregulates mitophagy and increases the clearance of damaged mitochondria in induced-neurons derived from embryonic stem cells and in SH-SY5Y neuroblastoma cells." (PMID 37957154, 2023). "We utilised the neuroblastoma SHSY5Y cell line and showed that knockdown of USP30 could be demonstrated to enhance the mitoKeima signal, indicating changes in the mitophagy pathway, in agreement with the other studies." (PMID 34704599, 2021).
liver cancer (4 papers, 2021 to 2025). An epithelial or non-epithelial malignant neoplasm that arises from the liver. "The dual localization of USP30 was also confirmed in additional malignant cell lines, including HepG2 (liver cancer) and HeLa (cervical cancer), as well as in the non‐transformed HEK293 cell line." (PMID 41306556, 2025). "Previous studies have demonstrated that dysregulation of USP30 in mice with high‐fat diet promotes lipogenesis and liver cancer progression through IKKβ–USP30–ACLY axis." (PMID 41306556, 2025). "High USP30 levels enhance the proliferation, invasion, and migration capacities of HCC cells, positioning USP30 as a potential diagnostic and therapeutic target for liver cancer." (PMID 40918504, 2025). "Gu’s study identified an IKKβ-USP30-ACLY axis that plays an essential role in the lipogenesis and liver cancer." (PMID 34344378, 2021).
Alzheimer disease (3 papers, 2022 to 2025). A progressive, neurodegenerative disease characterized by loss of function and death of nerve cells in several areas of the brain leading to loss of cognitive function such as memory and language. "In Alzheimer’s disease models, miR-137-5p-mediated USP30 suppression reduces hippocampal and cortical neuronal apoptosis, effects partially reversible by USP30 overexpression." (PMID 40918504, 2025). "This review examines Ubiquitin‐Specific Protease 30 (USP30) as a master regulator of mitophagy with therapeutic promise in Alzheimer's disease (AD) and Parkinson's disease (PD)." (PMID 39840724, 2025). "For example, induction of mitophagy by the small molecule compounds kinetin, DFP, Urolithin A, UMI-77 and an inhibitor of USP30 at multiple steps in the mitophagy pathway has been considered a potential treatment for neurodegenerative diseases, including PD and Alzheimer's disease (AD)." (PMID 38933121, 2022).
lung carcinoma (3 papers, 2021 to 2025). "Although showing affinity for multiple DUBs including USP14, USP10, and UCHL5, functional studies reveal its cytotoxic effects in lung cancer cells specifically depend on USP30 inhibition." (PMID 40918504, 2025). "Taken together, these results indicate that aumdubin inhibits DUBs, including mitochondrial USP30, in lung cancer cells." (PMID 34381024, 2021). "In the current study, we provide evidence that aumdubin, a new auranofin derivative, inhibits the mitochondrial outer membrane DUB USP30 and consequently induces Bax-dependent mitochondrial apoptosis in human lung cancer cells in vitro and in vivo." (PMID 34381024, 2021). "USP30 inhibition has also been shown to promote aumdubin-induced apoptosis of lung cancer cells." (PMID 36474192, 2022). "The USP30 inhibitor auranofin demonstrates therapeutic potential by increasing BAX ubiquitination and mitochondrial localization, inducing BAX-dependent apoptosis in lung cancer cells." (PMID 40918504, 2025).
oral squamous cell carcinoma (3 papers, 2022 to 2025). "In recent years, USP30 was also shown to be pro-carcinogenic in oral squamous cell carcinoma and associated with poor prognosis." (PMID 38146008, 2024). "For example, the use of nano delivery systems to deliver USP30 inhibitors, as demonstrated in oral squamous cell carcinoma, could improve the therapeutic efficacy by enhancing the delivery and targeting of inhibitors to cancer cells." (PMID 40918504, 2025).
pulmonary disorders (3 papers, 2022 to 2025). "The enzyme’s disease-associated roles extend beyond oncology to neurodegenerative disorders, pulmonary diseases, and inflammatory conditions, positioning USP30 as a compelling therapeutic target." (PMID 40918504, 2025). "Recently, emerging physiological roles of USP30 in neurodegenerative diseases, cancer, and pulmonary disorders have been reported, and mechanistic studies indicated the therapeutic potential of USP30 inhibitors." (PMID 35308234, 2022). "For the treatment of pulmonary disorders, the study in Mission Therapeutics of USP30 inhibitor is already in the pre-clinical stage." (PMID 35308234, 2022). "And USP30 inhibitors are already in preclinical stages in treating lung diseases, suggesting they may have potential in treating lung diseases." (PMID 40918504, 2025). "Additionally, USP30 inhibitors have been explored as a treatment for pulmonary disorders." (PMID 40709564, 2025).
brain injury (2 papers, 2023 to 2025). Acute and chronic (see also brain INJURIES, CHRONIC) injuries to the brain, including the cerebral hemispheres, CEREBELLUM, and brain STEM. "USP30 has been shown to hinder mitochondrial quality control and worsen oxidative damage following traumatic brain injury." (PMID 40709564, 2025).
diabetes (2 papers, 2019 to 2021). "It would be interesting to evaluate the if dual suppression of pexophagy and mitophagy by USP30 occurs in diabetes and its functional implications in CVD." (PMID 34440882, 2021). "Further research is needed to evaluate the precise role of USP30 in diabetes and CVD." (PMID 34440882, 2021). "We observed that LV expression of Mief1 and USP30 were significantly reduced in diabetic mice, although several other genes assessed (Mief2, Park2 and Park6) were not affected by the presence of diabetes." (PMID 31798462, 2019).
leukemia (2 papers, 2022 to 2025). A malignant (clonal) hematologic disorder, involving hematopoietic stem cells and characterized by the presence of primitive or atypical myeloid or lymphoid cells in the bone marrow and the blood. "In short, combining USP30 inhibitors with AKT/mTOR compounds in treating leukemia warrants further investigation." (PMID 35250566, 2022). "The apoptosis in treated cells suggests that USP30 inhibitors combined with AKT/mTOR inhibitors might prove a benefit in treating leukemia." (PMID 35250566, 2022). "Overall, this research revealed the connections between Parkin, USP30, and AKT signals, proving that USP30 inhibitors may be effectivein leukemia treatment." (PMID 35250566, 2022). "We next asked whether USP30 could be a viable target to synergize with AKT/mTOR inhibitors for leukemia treatment." (PMID 35250566, 2022). "Furthermore, We performed a chemical screening, suggesting that USP30 inhibitors may synergize with AKT/mTOR inhibitors in treating leukemia." (PMID 35250566, 2022). "Chemical screening data suggest potential therapeutic synergy between USP30 inhibitors and AKT/mTOR pathway inhibitors for leukemia treatment, positioning USP30 as a novel therapeutic target requiring further investigation in combinatorial regimens." (PMID 40918504, 2025). "Pharmacological USP30 inhibition reduces AKT levels in both HeLa Parkin USP30 cells and Jurkat T leukemia cells under mitochondrial stress or chemotherapy, promoting apoptosis." (PMID 40918504, 2025). "Taken together, we demonstrated that Parkin and USP30 might regulate the AKT/mTOR signaling and cell survival during mitophagy, suggesting USP30 may serve as a potential drug target for leukemia treatment." (PMID 35250566, 2022). "Moreover, inhibiting USP30 decreased AKT levels in Hela Parkin USP30 cells and Jurkat T leukemia cells during mitochondrial stress and chemotherapies, theraby inducing cell apoptosis." (PMID 35250566, 2022).
bladder cancer (1 paper, 2024). "Although we validated this interaction and established the existence of mutual interaction between Parkin and USP30 in BLCA cells, it remains unclear whether USP30 is involved in the Parkin-mediated regulation of catalase in bladder cancer." (PMID 38424181, 2024).
Cerebral ischemia (1 paper, 2021). Restriction of arterial blood supply to the brain associated with insufficient oxygenation to support the metabolic requirements of the tissue. "Our results suggest that USP30 is a promising target for the development of innovative therapeutic regimens for cerebral ischemia-reperfusion injury." (PMID 33609088, 2021). "Our results suggest that overexpression of USP30 may be a promising strategy for the treatment of disorders whose etiology is based upon cerebral ischemia-reperfusion injury." (PMID 33609088, 2021). "We demonstrated that overexpression of USP30 attenuated OGDR-induced mitochondrial fragmentation, suggesting that USP30 overexpression is beneficial for cerebral ischemia-reperfusion injury through maintaining mitochondrial structure integrity." (PMID 33609088, 2021).
colon adenocarcinoma (1 paper, 2025). "To investigate the role of USP30 in tumor immunity, we inoculated MC38 murine colon adenocarcinoma cells into both USP30CKO and control USP30WT (USP30flox/flox; LckCre−) mice." (PMID 40815646, 2025).
colon cancer (1 paper, 2025). "However, we found that USP30 deletion markedly improved mitochondrial fitness and partially restored effector function in exhausted CD8+ T cells in a colon cancer setting." (PMID 40815646, 2025).
diabetic foot ulcers (1 paper, 2025). "Considering that USP30 is upregulated in the skin tissues of patients with diabetic foot ulcers, targeting USP30 with the inhibitor MF-094 seems to be promising for promoting wound healing in diabetic rats and suppressing NLRP3 inflammasome activation." (PMID 40307577, 2025).
ischemia (1 paper, 2025). A hypoperfusion of the BLOOD through an organ or tissue caused by a PATHOLOGIC CONSTRICTION or obstruction of its BLOOD VESSELS, or an absence of BLOOD CIRCULATION. "For example, USP30's mitochondrial anchoring is critical for its anti-fission function, yet ischemia-induced displacement disrupts this protective role." (PMID 40529211, 2025).
lung adenocarcinoma (1 paper, 2022). A carcinoma that arises from the lung and is characterized by the presence of malignant glandular epithelial cells. "In lung adenocarcinoma cells, siRNA screen identified USP30 as one of the strongest hits involved in the hepatocyte growth factor (HGF)-induced cell scattering response, implying a role of USP30 in cancer cell metastatic." (PMID 35308234, 2022).
maternally-inherited Leigh syndrome (1 paper, 2026). "METHODS: Cybrids cells harboring mutant m.8993T > G mtDNA - common cause of NARP syndrome and maternally inherited Leigh syndrome (MILS) - were treated with USP30 inhibitor MF-094 under glycolytic and oxidative phosphorylation conditions." (PMID 41587019, 2026).
melanoma (1 paper, 2023). A malignant, usually aggressive tumor composed of atypical, neoplastic melanocytes. "Importantly, further analysis of CRISPR KO B16 melanoma cells confirmed that targeted suppression of ATXN3 and USP30 dramatically reduced PD-L1 expression." (PMID 38038129, 2023).
peroxisome biogenesis disorder (1 paper, 2025). "Research indicates that USP30 plays a significant role in the pathogenesis of various diseases, including cancers, neurodegenerative disorders, and peroxisome biogenesis disorders (PBDs)." (PMID 40918504, 2025).
pulmonary fibrosis (1 paper, 2022). Chronic progressive interstitial lung disorder characterized by the replacement of the lung tissue by connective tissue, leading to progressive dyspnea, respiratory failure, or right heart failure. "Thus, inhibition of USP30 may represent an actionable target to correct the PINK1/Parkin defect-associated pathologies of pulmonary fibrosis." (PMID 35308234, 2022). "USP30 inhibitors promoting mitophagy act with comparable efficiency in the lung fibrosis model to the pirfenidone which is a therapy approved in IPF treatment." (PMID 35308234, 2022).
subarachnoid hemorrhage (1 paper, 2024). A serious neurological disorder characterized by intracranial hemorrhage into the subarachnoid space. "The inhibition of USP30 has been found to play a significant role in modulating mitochondrial dynamics and autophagy, offering protection against early brain injury following subarachnoid hemorrhage." (PMID 39726593, 2024).
urothelial carcinoma of the bladder (1 paper, 2025). "USP30 is related to the occurrence and development of tumors, but current research may still be in the preliminary stage, and its specific role and mechanism in urothelial carcinoma of the bladder need further investigation." (PMID 40918504, 2025).
viral infection (1 paper, 2023). "As per viral infection, NIC and virus treated cells (at 48 h) also saw an up-regulation of GABARAPL1, MAP1LC3A, USP30, BMF, and TBK1; WDR81 was also down-regulated in the NIC and virus treatment at 48 h." (PMID 37901834, 2023).
cancer (16 papers, 2015 to 2026). A tumor composed of atypical neoplastic, often pleomorphic cells that invade other tissues. "USP30, a mitochondrial outer membrane deubiquitinase, has been implicated in neurodegeneration and cancer, but its role in endothelial function remains unexplored." (PMID 41104980, 2026). "USP30 can cause the accumulation of dysfunctional mitochondria in pathological states, and its inhibition has emerged as a promising therapeutic strategy to enhance mitophagy in NDDs and cancer." (PMID 40750884, 2025). "Through metabolism-related gene set enrichment analysis, we identified USP30 as a key modulator of glucose metabolism in cancer cells." (PMID 41688443, 2026). "To elucidate the functional significance of USP30 nuclear localization in suppressing cancer stemness and chemoresistance, we performed comprehensive functional analyses comparing WT USP30 with various USP30 mutants." (PMID 41306556, 2025). "Intriguingly, forced nuclear localization through NLS addition significantly enhanced USP30's ability to suppress cancer stemness and chemoresistance, while cytoplasmic retention or nuclear exclusion abolished these effects." (PMID 41306556, 2025). "It has been reported that GNPAT can recruit the deubiquitinase ubiquitin‐specific protease 30 (USP30) to stabilize the DRP1 protein in cancer." (PMID 40709564, 2025). "Subsequently, we investigated the role of nuclear USP30 in cancer progression and metastasis in vivo." (PMID 41306556, 2025). "The cytoplasmic‐to‐nuclear USP30 ratio was significantly higher in cancer cells compared to normal counterparts." (PMID 41306556, 2025). "Our findings establish USP30 as a critical regulator of mitophagy and a promising therapeutic target for reversing T cell exhaustion and enhancing the efficacy of cancer immunotherapy." (PMID 40815646, 2025). "This study resolves a key knowledge gap regarding USP30's nuclear functions and provides mechanistic insight into mitochondrial‐nuclear communication in cancer." (PMID 41306556, 2025). "Within the nucleus, USP30 exerts tumor‐suppressive effects by inhibiting cancer stemness and chemoresistance in TNBC cells." (PMID 41306556, 2025). "Drugs targeting USP1 and USP30 are in clinical development for cancer and kidney disease respectively." (PMID 35737447, 2022). "Nuclear‐localized USP30 suppresses cancer stemness, chemoresistance, and metastasis in TNBC models." (PMID 41306556, 2025). "Given the prevalence of dual‐localization proteins at the mitochondria‐nucleus interface and the established roles of USPs in cancer signaling, we hypothesized that USP30 may exert non‐canonical nuclear functions." (PMID 41306556, 2025). "USP30 has been proven to play a role as a cancer inducer in previous studies." (PMID 38146008, 2024). "Putting these results together, it can be seen that USP30 may be a valuable target for combinatorial anti-cancer therapy." (PMID 35308234, 2022). "The increase in Parkin-dependent mitophagy indicates that USP30 could be a drug target in cancer treatment." (PMID 35250566, 2022). "Moreover, depletion of USP30 sensitizes cancer cells to the drug ABT-737 via regulating the BAX/BAK-dependent apoptosis pathway, without needing the Parkin overexpression." (PMID 35308234, 2022). "Physiological role of USP30 in cancer and autophagy-related disorders." (PMID 35308234, 2022). "Further investigation of USP30’s function in regulating AKT/mTOR signaling may offer new therapeutic approaches in cancer treatment." (PMID 35250566, 2022). "Importantly, our data suggest that the link between USP30 and cell death pathways extends beyond this setting, as its depletion also sensitizes cancer cells against cell death induced by BH3-mimetics." (PMID 25739811, 2015). "Targeting USP30 represents a promising, mitochondria-directed strategy to restore T cell function in exhausted states and may enhance the efficacy of immunotherapies in cancer." (PMID 40815646, 2025).